PDCD1 (programmed cell death 1)
Diseases named in the same sentence as PDCD1 in open-access papers (continued):
Sharing a sentence is not in itself a finding about the gene and the disease.
tumor (continued). "Following coculture with E0771-Her2 tumor cells, A1R CAR T cells exhibited significantly increased production of IFNγ and TNF and increased expression of effector related genes PD-1 (Pdcd1), TIM-3 (Havcr2), Gzmb and Irf4 compared to control and A3R CAR T cells." (PMID 40610421, 2025). "Additionally, elevated expression of immune checkpoint genes (e.g., PDCD1 and CTLA-4) in the high MDK-NCL group suggests that this pathway might promote immune evasion by enhancing the tumor’s dependence on checkpoint mechanisms." (PMID 40396179, 2025). "Our mechanistic study revealed that TBC1D1-mediated inhibition of CTL function could be attributed to the upregulation of various immune checkpoint molecules, including ARG1, CD68, PDCD1, CD274, TGFB1, and CTLA4, collectively impeding the anti-tumor immune response." (PMID 38529286, 2024). "Interestingly, IL7R− γδ TRM upregulates inhibitory molecules CTLA4 and PDCD1 in the TME more than IL7R+ γδ TRM, indicating that IL7R+ TRM may sustain longer life and provide a longer-lasting anti-tumor effect." (PMID 39454432, 2024). "Furthermore, an analysis utilizing the TSIDB database uncovered a significant correlation between AEG-1 and several key factors, including the tumor-promoting cell Th2, immune activator IL6, CXCR4, immunosuppressants CTLA4, IL1, IDO1, LAG3, PDCD1, TGFB1, and the DHC molecule HLA-DPA1." (PMID 39483471, 2024). "Therefore, it can be speculated that CD27, PDCD1, TMIGD2 and TNFRSF25 may participate in tumour immunity by regulating IMCPs." (PMID 37849388, 2023). "We initially examined CSF3 and PDCD1 expression in diverse tumor tissue against normal tissue, revealing that PDCD1 expression was greater in the majority of tumor tissue versus unpaired/paired normal tissue, whereas CSF3 expression was lower in the majority of tumor tissue." (PMID 37644514, 2023). "Our analysis suggests that, of the three immune checkpoints considered, PDCD1/CD274 is the least important determinant of the exhausted CTL state; however, our model remains compatible with PDCD1/CD274 playing a role in CTL exhaustion at early time points after CTL infiltration of the tumor." (PMID 37182110, 2023). "In the third study, while PD1-disrupted cells persisted in patients for 4 four weeks after infusion, no objective conclusions could be made on the effect of PDCD1 disruption on anti-tumor activity due to the small trial size and short duration of study." (PMID 37190012, 2023). "CD8 Tex with elevated expression of multiple inhibitory receptors (PDCD1, CTLA4, LAG3, TIGIT, HAVCR2) and Tregs with high expression levels of FOXP3, TIGIT, and CTLA4 were enriched in the ESCC TME, which contributed to tumor immune escape and immunotherapy resistance." (PMID 37187751, 2023). "Besides, they identified a cluster of cytotoxic GZMB CD4+ T cells that expressed high levels of PDCD1 and CTLA4, suggesting that this population could be involved in the anti-tumor response after immunotherapy." (PMID 36414693, 2023). "In B16 melanoma tumors, dual LAG-3 and PD-1 depletion on TILs diminished tumor-induced tolerance and yielded higher responses compared to single-checkpoint-deficient mice, eliminating 80% of tumors (vs. 40% elimination in PDCD1−/−, and no tumor growth control in wild-type and LAG-3−/−mice)." (PMID 37345056, 2023). "Therefore, we further compared the expression of immune checkpoint genes in tumor tissues of the high SIRGs score group and the low SIRGs score group and found that PD-L1, CTLA-4, HAVCR2, LAG3, TIGIT and PDCD1 were also up-regulated in the high SIRGs score group." (PMID 36052090, 2022). "Notably, the drug promoted dendritic cell and, to a lesser extent, T-cell infiltration in vivo, yet failed to sensitize tumor cells to programmed cell death-1 inhibition." (PMID 35634329, 2022). "Neither the type of GBM tumor nor patient gender affected PDCD1 expression." (PMID 36591276, 2022).
tumor (continued). "The immune checkpoint molecules programmed cell death protein 1 (PD-1, also known as PDCD1) and programmed death-ligand 1 (PD-L1, also known as CD274) are a receptor-ligand system that interconnects in the tumor microenvironment to block anti-tumor immune responses." (PMID 35479647, 2022). "Immune checkpoints such as cytotoxic T-lymphocyte antigen 4 (CTLA-4), programmed cell death 1 (PD-1), and programmed cell death ligand 1 (PDL-1) are negative regulators of immune activation, allowing cancer cells to evade immune surveillance, thereby enabling unchecked tumour growth." (PMID 35200573, 2022). "Besides, C1QTNF6 is obviously correlated with many immune checkpoints including LAG3, PDCD1, CTLA4, which suggested that C1QTNF6 may act as a new immune checkpoint for tumor immunity." (PMID 35401204, 2022). "Furthermore, higher expression of VSIR was discovered in C02 and C06 as well, indicating clusters with higher expression of PDCD1 and VSIR may tend to be downregulated by increased expression levels of tumor PD-L1." (PMID 33754038, 2021). "Otherwise, tumor cells in hypoxia could inhibit TAMs activation via HLA-G/LILRB interactions, assist TAMs polarization via CD44-related communication, and inhibit T-cell activation via PDCD1 and TIGIT." (PMID 34956900, 2021). "There is evidence that T cells lose their effector function and ability to kill tumor cells when stimulated by tumor antigens, which may be due to the increasing diversity and number of inhibitory receptors, including CD274, PDCD1LG2, HAVCR2, CTLA4, LAG3, PDCD1, TIGIT." (PMID 33592580, 2021). "The promotion of an immunosuppressive phenotype by PDCD1 rs10204525 C > T may also contribute to tumour development but has not as yet been characterised." (PMID 33808740, 2021). "Data from TCGA database may not precisely reflect the PD-1 (PDCD1) level of tumor cells, because there are a lot of infiltrating immune cells in tumor tissues." (PMID 34326692, 2021). "ICB therapies targeting programmed cell death-1 (PD-1, commonly expressed on T cells within the TME) or its ligand (PD-L1, commonly expressed on tumor and stromal cells within the TME), have been shown to rescue effector CD8+ T cell function for effective tumor cell killing." (PMID 33968758, 2021). "In addition, tumor-infiltrating TRM cells express several immune checkpoint molecules (for example, CTLA-4, TIGIT, TIM-3, LAG3 and programmed cell death-1 [PD-1]), indicating that they might respond effectively to immune checkpoint blockers." (PMID 32695313, 2020). "Cancer immunotherapies that inhibit negative immune feedback, such as those targeting programmed cell death 1 (PD1)/programmed cell death-ligand 1 (PDL1) and cytotoxic T-lymphocyte-associated protein 4 (CTLA4), have proven efficacious against several tumor types." (PMID 31300050, 2019). "PD-1 (PDCD1) is a type I transmembrane glycoprotein receptor, part of the CD28/CTLA-4 immune checkpoint receptor family, expressed on peripheral blood mononuclear cells and activated tumor-infiltrating mononuclear immune cells and responsible for the down-regulation of T-cells." (PMID 31443471, 2019). "For instance, programmed cell death-1 (PD-1)/PD-L1 axis, and the cytotoxic T-lymphocyte antigen 4 (CTLA-4)/B7 axis, which contribute cancer cell protection through their suppressive role in tumor microenvironment and negatively regulate cancer cell eradication by immune destruction methods." (PMID 28785557, 2017). "Notably, the interaction between the programmed cell death 1 (PD‐1) receptor and its ligand PD‐L1 is among the most common and extensively studied mechanisms; this interaction inhibits the immune response of CD8+ cytotoxic T cells, thereby enabling tumor cells to evade immune surveillance." (PMID 40365984, 2025). "Therefore, CD27, PDCD1, TMIGD2 and TNFRSF25 may participate in tumour immunity by regulating IMCPs." (PMID 37849388, 2023).
tumor (continued). "Interestingly, FDX1 was significantly negatively correlated with the expression of many immune checkpoint genes in ACC, especially PD-1 (PDCD1), PD-L1(CD274), CTLA4 and other important immunotherapy targets, which may also be closely related to the immune escape mechanism of ACC tumor cells." (PMID 35991547, 2022). "In the tumor microenvironment, the binding of programmed cell death 1 (PD‐1) and PD‐L1 has a negative‐modulating effect on T cells and reduces the production of cytokines, thereby inhibiting cytotoxic T‐cell‐mediated anti‐tumor immunity and tumor clearance ability." (PMID 35355427, 2022). "Thus, the PD-1cKO mice, which enables deletion of Pdcd1 following tumor implantation and has normal baseline frequencies of EM CD4 and CD8 T cells, can be a useful model to investigate both tumor cell-intrinsic and tumor cell-extrinsic factors leading to regression of large tumors." (PMID 34912335, 2021). "Moreover, we found that POLE expression in cancers significantly correlated with an immunosuppressive tumor microenvironment, higher intratumoral heterogeneity, and expression of immune checkpoint genes PDCD1, CTLA4, and CD86, possibly mediated via the JAK/STAT and Notch signaling pathways." (PMID 34950188, 2021). "As the IL2rα and PDCD1 loci can be efficiently repurposed to secrete IL-12P70 in a controlled and tumor-dependent manner in vitro, we tested whether the IL-12P70 secreting TRACCAR T cells could transiently and locally deliver IL-12P70 to an engrafted tumor in a xenogenic mouse model." (PMID 31723132, 2019). "Therefore, PDCD1 overexpression might not carry a uniform prognostic meaning, but rather reflect the dynamic interplay between immune activation and inhibition in the tumor context." (PMID 40869918, 2025). "In addition, recent studies have shown that patients treated with ICIs can develop systemic bone loss or localized bone lesions, which are unlikely to be attributed to tumor‐induced osteolysis, suggesting that programmed cell death 1 (PD‐1) blockade may have an impact on the bone remodeling process." (PMID 40989575, 2025). "Researchers found that SEMA6D is predominantly expressed by non-hematopoietic cells, especially tumor cells, and shows a strong negative correlation with CD8A, PDCD1, IFNG and GZMB." (PMID 41438751, 2025). "In NEPC samples, canonical immune checkpoint genes PDCD1, CD274 and PDCD1LG2 were absent, while CD276 was uniformly expressed across tumour regions." (PMID 40677104, 2025). "In contrast, CDH18 showed negative correlations with TNFSF14, TNFSF15, PDCD1, TNFRSF14, and CD44, genes reported to play critical roles in tumor inhibition." (PMID 40017628, 2025). "We found that the expression of PD-1 (PDCD1/CD279) was lower in ESCA samples and that the differences in the corresponding ligand (tumor cell) CD274 (PD-L1) were non-significant across patients and groups." (PMID 39076970, 2024). "In contrast, we did not see the differential expression of LAG3, PDCD1, and HAVCR2 genes in the blood of any patient groups, suggesting differences between the tumor and blood circulation immune microenvironments." (PMID 37762493, 2023). "CD274 expression was found to be down-regulated in tumor tissues (P < 0.05), while TIGIT, PDCD1, CTLA4 and LAG3 expression in tumor tissues were not statistically different." (PMID 36959799, 2023). "We used qPCR to analyze the ALDH3A2, PDCD1, PDCD1LG2, and CTLA-4 mRNA expression levels in 52 tumor tissues, which indicated a negative spatial correlation between ALDH3A2 and PDCD1 (R2 = 0.3576), PDCD1LG2 (R2 = 0.3878), and CTLA-4 (R2 = 0.2556)." (PMID 33148208, 2020). "Looking at all studies across all tumor entities, patients whose tumors express CD247 appear to respond better to PDCD1 blockade than patients without CD247 expression." (PMID 33240813, 2020).
tumor (continued). "Furthermore, FAM114A1-low patients presented significantly greater CD8+ T-cell infiltration, independent of tumor stage, and CD274 and PDCD1 expression, according to multivariate logistic regression analysis." (PMID 41249116, 2025). "Furthermore, PTGER4's negative correlation with immune checkpoints (PDCD1, CTLA4) underscores its potential to counteract immune exhaustion, a phenomenon critical for sustaining anti‐tumour immunity." (PMID 41284374, 2025). "Consistent with human CD8 GZMB+, the human-like CD8 GZMB+ clusters (Cluster0, 1) also had significantly higher Ctla4, Tox and Tox2 expression in the tumor environment injected with Macro CD5L+, while the expression of Pdcd1 (PD1) was not different between the two groups." (PMID 38245530, 2024). "Healthy adult bone marrow Erythroid cells also differ from the tumor-induced Erythroid cells, as they do not express any PDCD1 (PD-1) or CD274 (PD-L1) genes, which suggests restricted immunosuppression by healthy adult bone marrow Erythroid cells compared with the tumor-induced ones." (PMID 39038020, 2024). "Anti-PDCD1 antibodies only have the ‘Immunostimulant’ effect by activating Teff cells, whereas anti-CD274 mAbs with a functional Fc mediated ADCC directly against tumor cells improve tumor killing without unwanted toxicities." (PMID 37215135, 2023). "by using TIMER 2.0 online tool and adjusting tumor purity, we found that SPTBN1 expression had negative correlations with the expression levels of TNFSF9 (R =-0.238, p = 2.31E-07), PDCD1 (R =-0.191, p = 3.81E-05) and CTLA4 (R =-0.16, p = 5.67E-04) in KIRC (revised_Figure 6B)." (PMID 37013511, 2023). "With our model we were able to obtain good fits if the exhausted state was correlated with HAVCR2 or LAG3 but not with PDCD1/CD274, which was due to the early peak of Pdcd1 and Cd274 transcription that was already well in decline on day 5 while CTL numbers in the tumor remained high." (PMID 37182110, 2023). "XA511 alone could not inhibit tumor growth, the combination treatment with anti-PD1 antibody, which targets programmed cell death-1 protein, significantly reduced tumor growth." (PMID 35145519, 2022). "However, alterations in this pathway were consistently high regardless of changes in tumor purity, and PDCD1LG2 and PDCD1 expression." (PMID 34100771, 2021). "One strategy is to knock them out using multiplexed CRISPR-based gene editing or other non-viral methods: e.g., the inactivation of PDCD1 in melanoma-reactive CD8+ T cells and fibrosarcoma-reactive polyclonal T cells using TALEN-enhanced T-cell infiltration in the tumor site and tumor control." (PMID 32937956, 2020). "Daily challenges of TRACCAR T cells edited by either IL2rα or PDCD1 TALEN in the absence of the IL-12P70 matrix (TRACCAR_CD25 and TRACCAR ΔPD1, black open circles) resulted in suboptimal tumor cell control and eventual tumor cell outgrowth." (PMID 31723132, 2019). "In lymph nodes of the TCL1tg mice, a significant correlation between PDCD1 or LAG3 expression on T cells and tumour infiltration could be observed (Fig3), while there was no such correlation in the peripheral blood or spleen (not shown)." (PMID 25940792, 2015). "Tumor size of mice treated with TC-1/A9 non-inflamed tumors and the drug effects of an antigen, a toll-like receptor-3 agonist (PIC), and an immune checkpoint inhibitor (anti-programmed cell death 1 antibody) were modeled using Monolix and following a middle-out strategy." (PMID 34680196, 2021).
cancer (1,707 papers, 2014 to 2026). A tumor composed of atypical neoplastic, often pleomorphic cells that invade other tissues. "Immune checkpoints such as cytotoxic T-lymphocyte-associated protein 4 (CTLA-4), programmed cell death 1 (PD-1), and programmed cell death ligand 1 (PD-L1) have been targeted in cancer therapy, however, the efficacy of these interventions remains limited." (PMID 41639053, 2026). "The analysis of nsSNPs in the PDCD1 gene revealed cancer-specific associations, including G124V and G224V in SKCM, as well as R86P in OV." (PMID 40149458, 2025). "These agents target immune checkpoints like cytotoxic T-lymphocyte-associated protein 4 (CTLA-4) and programmed cell death 1 or its ligand (PD-1/PD-L1), disrupting immunosuppressive pathways and immune homeostasis critical for cancer progression." (PMID 41278277, 2025). "The benefits of immunotherapy in the treatment of cancer are suggested by the clinical success of blocking antibodies that target p programmed cell death-1 (PD-1) and cytotoxic T lymphocyte-associated antigen-4 (CTLA-4)." (PMID 40230883, 2025). "CD8-C4-Tem-PDCD1 is associated with the complement pathway, hypoxic stress, and cancer cells migration and invasion." (PMID 39354287, 2025). "Using the cBioPortal web server, cancer-specific nsSNPs associated with the PDCD1 gene were identified." (PMID 40149458, 2025). "This demonstrated the association of the PDCD1/LAG3 signature with potentially immunogenic “hot” cancers." (PMID 39030301, 2024). "Immune checkpoint inhibitors (ICIs) (such as cytotoxic T-lymphocyte-associated protein 4 (CTLA-4), programmed cell death-1 (PD-1), and PD-L1 inhibitors) have emerged as important strategies for various cancers." (PMID 39351236, 2024). "We discovered that JAK2-mutated cancers displayed upregulated expression of immune checkpoint molecules (such as PDCD1, CD274, CTLA4, and TIGIT) compared with JAK2-wild tumors." (PMID 38200372, 2024). "Searching The Cancer Genome Atlas (TCGA) database reveals widespread transcription of the PDCD1 gene, which encodes PD-1, in 17 cancers including CRC." (PMID 38533512, 2024). "Programmed cell death-1 (PD-1) is associated with cancer immune checkpoint mechanisms, and anti-PD-1 antibodies have been used widely for immunotherapy in various types of cancer, including HCC." (PMID 38781172, 2024). "ICIs target immune checkpoint proteins like cytotoxic T-lymphocyte-associated protein 4 (CTLA-4), programmed cell death-1 (PD-1), and programmed cell death-ligand 1 (PD-L1), which cancer cells exploit to evade immune detection." (PMID 38392565, 2024). "Recently, a pivotal role for PCSK9 in cancer immunotherapy was proposed based on the finding that PCSK9 inhibition was associated with enhancing the antigen presentation efficacy of target programmed cell death-1 (PD-1)." (PMID 37860186, 2023). "A meta-analysis shows the PDCD-1 rs36084323 SNP is associated with decreased cancer risk (GG + GA vs. AA, OR = 0.903, 95% CI = 0.819–0.995, P = 0.038)." (PMID 37131179, 2023). "For example, a heatmap is used to visualize the correlation of PDCD1 (encodes PD-1 protein) expression and known immunomodulators across a range of human cancers." (PMID 37457379, 2023). "PD-L1 encodes a ligand for PD-1 (aka Pdcd1), a receptor on T lymphocytes that suppresses cancer growth." (PMID 35865523, 2022). "Further studies are needed to determine the detailed pathways and mechanisms underlying the apoptotic role of Pdcd1 in cancer cells." (PMID 35190965, 2022). "For example, the PDCD1 gene encodes PD-1 which regulates the activation of T-lymphocytes and immune responses and has become a validated immunotherapeutic cancer target in the clinic." (PMID 36497468, 2022). "ICI drugs target the co-inhibitory receptors present on T cells, such as cytotoxic T lymphocyte-associated protein-4 (CTLA-4) and programmed cell death-1 (PD-1) or their ligand (PD-L1) expressed on cancer cells, by selectively blocking their interaction." (PMID 36556139, 2022).